MCL1 (MCL1 apoptosis regulator, BCL2 family member)
Diseases named in the same sentence as MCL1 in open-access papers (continued):
Sharing a sentence is not in itself a finding about the gene and the disease.
breast carcinoma (continued). "We investigated the role of FBXW7 and their substrates MCL1 and PLK1 in regulating the apoptotic response to paclitaxel treatment in breast cancer cells and their expression in breast cancer tissues." (PMID 27409838, 2016). "Dioscin-induced breast cancer cell death via AIF-facilitated caspase-independent pathway and the down regulation of anti-apoptotic proteins as Bcl-2, cIAP-1, and Mcl-1." (PMID 27751178, 2016). "This prompted us to consider FBXW7 as an important mediator of the paclitaxel response through the control of MCL1 and PLK1 degradation in breast cancer." (PMID 27409838, 2016). "Our data also highlight the potential for development and use of these compounds, including highly selective CDK9i, in treating ER+ve breast cancer through concurrent inhibition of MYB, MCL-1 and other regulators of apoptosis." (PMID 26812885, 2016). "This demonstrates that the positive modulation of Mcl-1 in CCA cells is dependent upon PI3K/AKT activation, as reported in breast cancer, nasopharyngeal carcinoma and rhabdomyosarcoma cells." (PMID 26296968, 2015). "MCL1 is an anti-apoptotic member of the BCL2 family and is known to be focally amplified in about 10.9% of cancers across multiple tissue types (e.g. breast cancer, lung cancer, etc.)and to increase tumor cell survival." (PMID 26636651, 2015). "In human breast cancers, up to 80% of MYC-amplified triple negative breast cancer (TNBC) cases harbor MCL1 co-amplification." (PMID 25784482, 2015). "Previous literature has demonstrated that Mcl-1 is a downstream target of epidermal growth factor (EGF) in many different types of cancer, including breast cancer." (PMID 24971890, 2014). "Previous literature has demonstrated that Mcl-1 is a downstream target of EGF in many different types of cancer, including breast cancer." (PMID 24971890, 2014). "Regulation of Mcl-1 by SRSF1 and 5 was also investigated in a second breast cancer cell line using MDA-MB-231 cells, described as having an invasive phenotype in vitro." (PMID 23284704, 2012). "So its involvement in the production of the anti-apoptotic form of Mcl-1 in the MCF-7 and MDA-MB-231 breast cancer cell lines is consistent with its known upregulation in breast cancer tissue." (PMID 23284704, 2012). "These molecular profiling analyses are mostly consistent with the notion that mechanisms leading to Mcl-1 transcription and expression are highly active in HER2 overexpressing breast cancers." (PMID 21899728, 2011). "The stability of anti-apoptotic proteins Mcl-1 and Bcl-2 was also assessed in these MDA-MB-468, MDA-MB-231 and MCF-7 breast cancer cells after treatment with CHX (200 μg ml–1)." (PMID 21730980, 2011). "Although MCL1 inhibition was reported to synergize with HER2-targeting drugs in breast cancer, the addition of MCL1i or BCL2i (up to 2 μM) failed to enhance the activity of trastuzumab in HER2-ampfiled GC cells." (PMID 40075071, 2025). "However, in tamoxifen-resistant breast cancer, EGR3 was upregulated and directly promoted expression of MCL1, contributing to therapy resistance." (PMID 40649712, 2025). "As an initial indication of potential predictive utility of the PRIMAB readouts, we showed a distinct staining in xenografted human breast cancer cells that are responsive to MCL-1 inhibitor, AZD5591, or not responsive to that treatment." (PMID 40507334, 2025). "Therefore, in the present study, we have assessed the effect of MOXI and MIM1, the Mcl-1 protein inhibitor used in one- as well as two-component models, on MDA-MB-231 breast cancer cells." (PMID 40892149, 2025). "Moreover, we uncovered BCL2 family proteins, including BCL2L1 and MCL1 as potential mechanisms for radiation resistance not only in MCF10A cells but also in multiple human and murine breast cancer cell lines." (PMID 38316463, 2024).
breast carcinoma (continued). "A similar effect is observed in PTEN null breast cancer cell lines where AKT inhibition combines with the MCL-1 inhibitor AZD5991 to increase cell death independent of upstream PI3K pathway regulation." (PMID 39284898, 2024). "High levels of Mcl-1 may further correlate with resistance to ABTs, as reported for cells of ALL, CLL, and lung and breast cancers." (PMID 38542429, 2024). "Therefore, we presumed that MCL-1 and MYC work cooperatively in HGBCL, as reported in a previous study on breast cancer." (PMID 38918775, 2024). "To confirm if MCL1 is the key regulator of RMC-6272-induced apoptosis in breast cancer cells, we overexpressed MCL1 in MCF-7 and ZR-75-1 cells, and observed that MCL1 overexpression was sufficient to rescue cells from RMC-6272-induced cleavage of PARP, as compared with the Luciferase control." (PMID 37264081, 2023). "To explore whether the decreased expression of MCL-1 and increased cell apoptosis after ABGE treatment were related to the ROS in ER+ breast cancer, we examined the mitochondrial and intracellular ROS levels in MCF-7 cells." (PMID 37352173, 2023). "S63845, either alone or in combination with inhibitors of oncogenic kinases, was found to be moderately effective in certain solid tumours, such as breast cancer and prostate cancer and SCLC derived cell lines that are express high levels of MCL-1 but low levels of BCL-XL." (PMID 36342579, 2023). "Therefore, this study approached breast cancer treatment with a dual-targeted therapy targeting HER2-mediated signaling (TZ treatment) and Mcl-1 mRNA (Mcl-1 nioplex treatment)." (PMID 37896184, 2023). "Here, we revealed that BCL2, BCL2A1, BCL2L2, and MCL1 but not BCL2L1 were overexpressed in estrogen receptor (ER)-positive breast cancer cells and clinical biopsies." (PMID 36853387, 2023). "Furthermore, MCL1 expression and amplification exceeded that of BCL2 and BCL2L1 (Bcl-xL) in clinical ER+ breast cancer samples." (PMID 35053443, 2022). "Notably, the frequency of MCL1 amplification and mRNA expression exceeds both BCL-2 (~9%) and BCL-XL (~27%) across all major subtypes of breast cancer, suggestive of a specific importance of MCL-1 in breast tumourigenesis." (PMID 35349392, 2022). "We therefore attempt to identify the molecular mechanisms governing this interplay, focusing our attention on MCL-1: the BCL-2 family anti-apoptotic member recently identified as involved in the control of cell invasion in several tumors, including breast cancer and PDAC." (PMID 35884957, 2022). "CAFs derived from breast cancers (bCAFs), regardless of subtype, express MCL-1 at a higher level than in normal fibroblasts." (PMID 36104324, 2022). "For example, it has been illustrated that pro-inflammatory cytokine interleukin (IL)-6 potently stimulates JAK/STAT signaling in breast cancer cell lines, and it has also been shown that both IL-6 and JAK/STAT signaling can potentiate MCL1 transcription in multiple cancer subtypes." (PMID 35349392, 2022). "Taken together, this highlights the intimate relationship between MCL-1 protein levels and NOXA expression which may be important for progression and drug resistance in breast cancer patients." (PMID 35349392, 2022). "A study from Strappazzon and colleagues found that GSK-3β phosphorylates MCL-1 to release AMBRA1, while HUWE1 promotes MCL-1 degradation in Hela cells and MCF7 breast cancer cells, highlighting the need for further studies to elucidate molecular mechanisms of AMBRA1 and mito-BCL-2 in mitophagy." (PMID 36237336, 2022). "Amplification/gain of MCL1 persists across breast cancers independent of the tumor stratification approach and is observed in up to 72% of breast cancer cases in online genomic data repositories." (PMID 35349392, 2022). "We demonstrated for the first time that the observed effects of MFLX on MDA-MB-231 breast cancer cells (growth inhibition and apoptosis induction) could be related to the drug’s ability to interact with MITF and Mcl-1 proteins." (PMID 36045272, 2022).
breast carcinoma (continued). "Apoptosis induction through Mcl-1 down-regulation in breast cancer cells was reliant on the activity of Bak, not Bax." (PMID 35053443, 2022). "In breast cancer cell lines, Mcl-1 expression was found necessary for the survival of 47% of breast cancer cells irrespective of the subtype." (PMID 35053443, 2022). "Molecular docking analysis (in silico), fluorescence image cytometry, and Western blot (in vitro) techniques were applied to assess the contribution of MITF and Mcl-1 proteins in the MFLX-induced anti-proliferative and pro-apoptotic effects on the MDA-MB-231 breast cancer cells." (PMID 36045272, 2022). "Furthermore, this research suggested that siMcl-1 was able to reduce 3nAG-induced Mcl-1 overexpression and sensitize 3nAGN-NSC cytotoxicity to MCF-7 human breast cancer cell lines by downregulating Mcl-1 mRNA via the apoptosis induction pathway." (PMID 35745769, 2022). "The antineoplastic agent docetaxel is synergistic with the Mcl-1 inhibitor S63845 in TNBC and HER2-amplified breast cancers, the first-generation pan Bcl-2 family inhibitor ABT-737 in ER+ breast cancer, and the Bcl-xL–specific inhibitor A-1331852 in a wide range of solid tumor types." (PMID 36381235, 2022). "Similarly, we also observed that when blocking BCL-xL with A-133, T47D cells survive through MCL-1, highlighting the importance of these two anti-apoptotic proteins in BH3 mimetics adaptation in breast cancer." (PMID 34359829, 2021). "In contrast, genes often associated with the basal-like subtype and a poor prognosis such as MCL1, CTNNB1, EGFR, or SOX4 were found in the basal-like patient GSM519217 suggesting that the generated networks are capable of extracting breast cancer subtype-specific features." (PMID 33706810, 2021). "Here we investigate the role of MCL-1 in clinically relevant breast cancer models and address whether the canonical role of MCL-1 in apoptosis, which can be targeted using BH3-mimetic drugs, is the major function for MCL-1 in breast cancer." (PMID 33785871, 2021). "Type I IFNs also upregulate the survival factors MCL1, the apoptosis regulator BCL2 family member (MCL1) and interferon alpha inducible protein 6 (IFI6, best known as G1P3) in myeloma and estrogen-receptor positive breast cancer, respectively, thus promoting poor patient outcome." (PMID 34571733, 2021). "Myeloid cell leukemia 1 (MCL1), an antiapoptotic BCL-2 family member, is overexpressed in many types of human tumors, including leukemia, breast cancer, prostate cancer, and ovarian cancer; and its expression correlates with disease grade and survival-predicting response to anticancer therapies." (PMID 34156978, 2021). "FASN inhibition, however, fails to sensitize breast cancer cells to MCL-1- and BCL-XL-selective inhibitors such as S63845 and A1331852." (PMID 34675185, 2021). "Thus, MCL-1 and BCL-xL clearly compensated for each other in ER+ breast cancer cells as the inhibition of one leads to cells escaping apoptosis through the other." (PMID 34359829, 2021). "Non-apoptotic functions for MCL-1 have been described in cardiomyocytes, pluripotent stem cells, breast cancer stem cells and neurons." (PMID 33785871, 2021). "Recently, we reported that levels of the endogenous MCL-1 inhibitor, NOXA, are uniformly depressed in HER2-amplified breast cancers, as a result of a co-amplified intronic microRNA that targets the estrogen receptor (ER), which in turn leads to loss of ER-driven NOXA transcription." (PMID 33589591, 2021). "With further investigation, the link between MCL1 and MARCH5 could shed light on the mechanism‐of‐action of MCL1 inhibitors and the development of stratification approaches in solid tumours, such as breast carcinomas." (PMID 32627965, 2020). "Previously, BS-181 was reported to induce G1-arrest and apoptosis, resulting from the down-regulation of G1 cyclin (cyclin D1) and anti-apoptotic proteins (MCL-1 and XIAP) in breast cancer cells and down-regulation of cyclin D1 and XIAP in gastric cancer cells." (PMID 33352782, 2020).
breast carcinoma (continued). "However, a limited number of studies also highlighted an MCL-1 dependency in solid tumors such as NSCLC and breast cancer cell lines, opening new avenues for the evaluation of MCL-1 inhibitors in these cancers." (PMID 33308268, 2020). "Similar to other MCL-1 inhibitors, AZD5991 demonstrated strong selectivity for hematological cancer cell lines, whereas only subsets of solid tumors were characterized as sensitive (NSCLC, breast cancer)." (PMID 33308268, 2020). "Research showing that Mcl-1 upregulation significantly contributes to resistance against widely used anticancer therapies including antitubulins, HER2-targeting agents, points to Mcl-1 as an important target in breast cancer therapy." (PMID 31404252, 2019). "In contrast to Mcl-1 upregulation upon treatment with VU661013, we did not see upregulation of Bcl-2 or Bcl-xL in ER+ breast cancer cells treated with the Mcl-1 inhibitor." (PMID 31595181, 2019). "In our own experiments we have observed that MDA-MB-231 breast cancer cells lines succumb to 20 μM A-1210477, yet it has been reported that they do not require MCL1 for survival." (PMID 30796196, 2019). "Further, Mcl-1 protein expression correlates with poor patient survival in breast cancers regardless of subtype." (PMID 31595181, 2019). "Furthermore, MCL-1 inhibitor mediated cell death was abrogated by caspase inhibition with Q-VD-OPh again showing on-target impact of these BH3-mimetics in breast cancer cells." (PMID 29339815, 2018). "This includes the use of small molecule MCL-1 inhibitors and knock-down/knock-out of MCL-1 in vitro and in vivo xenograft/genetically engineered mouse models to investigate the therapeutic potential of targeting MCL-1 in breast cancer." (PMID 30405205, 2018). "We next examined the impact of MCL1 si-NPs in parental ERα+ breast cancer treated with fulvestrant, first verifying Mcl-1 knockdown in parental HCC1428, MCF7, and T47D cells at 48 h post-treatment, revealing 70–90% fewer MCL1 transcripts as compared to cells treated with LUC si-NPs." (PMID 29343814, 2018). "To further investigate the therapeutic potential of these findings, we tested the impact of pharmacological inhibition of MCL-1 in established mammary tumours in vivo and found that MCL-1 inhibition or knock-down inhibited TN breast cancer growth in xenograft experiments." (PMID 29339815, 2018). "Interestingly, MCL1 mRNA levels were found to inversely correlate with BCL2 upon analysis of two large independent breast cancer data sets." (PMID 29339815, 2018). "The BCL-2, MCL-1, and BCL-XL pro-survival proteins and the pro-apoptotic BH3-only ligand BIM are contemporaneously over-expressed in a significant proportion of the different breast cancer subtypes including the more aggressive basal-like." (PMID 29099748, 2017). "In addition to inhibiting MCL-1, SC-2001 has been reported to induce cell death through SHP-1 dependent STAT3 inactivation in liver and breast cancer cells." (PMID 27086916, 2017). "We queried breast cancer samples in the TCGA database for those with expression information for both ERRF and MCL1, and found a significant inverse correlation between ERRF and MCL1." (PMID 28415602, 2017). "Taken together with the result that knockdown of MCL1 compromised lapatinib resistance mediated by ERRF knockdown, it is possible that ERRF downregulates MCL1 expression to promote apoptosis in breast cancer's response to lapatinib." (PMID 28415602, 2017). "Our results showing rescue of growth inhibitory effect of Mcl-1 knockdown in BOK and Mcl-1 depleted breast cancer cells suggest that BOK and Mcl-1 may be in a complimentary feedback loop." (PMID 29156771, 2017). "We checked the gene expression levels of MCL-1, MTDH, and EZH2 which are proven targets of miR-26a in breast cancer and could be responsible of its anti-proliferative effect." (PMID 27517917, 2016).
breast carcinoma (continued). "In a panel of breast cancer lines, the antitumor efficacy of MTI-31 was dependent on HER2+ and/or PIK3CAmut (HER2+/PIK3CAmut) status of the tumors and required mTORC2-specific modulation of Bim, MCL-1 and GSK3." (PMID 27563814, 2016). "To analyze FBXW7 expression and its relation to the relative abundance of substrates, and with prognostic variables in breast cancer, we performed immunohistochemistry for FBXW7, AURKA, Cyclin E, MCL1 and PLK1 in tissue microarrays containing up to 296 samples of breast carcinomas." (PMID 27409838, 2016). "We conclude that FBXW7 regulates the response to paclitaxel by targeting MCL1 and PLK1 in breast cancer cells and thus targeting these substrates may be a valuable adjunct for paclitaxel treatment." (PMID 27409838, 2016). "MCL-1 has previously been shown to be coexpressed with BIM across all subtypes of invasive breast carcinoma and this expression pattern was recapitulated in our panel of human breast cancer cell lines." (PMID 27931239, 2016). "Confirming this, we observed that treatment with A-1210477 alone induced death in MCL1-dependent breast cancer cells, but not in HCT116 cells, which are not dependent on MCL1." (PMID 26910119, 2016). "MCL-1 levels in triple-negative and HER2 breast cancers may provide a biomarker of response to routine chemotherapy (basal cancers) and anti-HER2 therapy (HER2 amplified cases)." (PMID 27931239, 2016). "Last, it has been found in breast cancer cells that ERK1/2 can phosphorylate and stabilize Mcl-1." (PMID 27517746, 2016). "Furthermore, we observed a synthetic lethal interaction between MCL1 and MARCH5 in MCL1-dependent breast cancer cells." (PMID 26910119, 2016). "Cisplatin- or etoposide-induced Noxa up-regulation, MCL-1 reduction, and apoptosis were also observed not only in HeLa cervical cancer cells, but also in MDA-MB-468 breast cancer cells, HN30 head and neck squamous carcinoma cells, and mouse embryonic fibroblasts." (PMID 27166195, 2016). "In conclusion, these data suggest that downregulation of Mcl-1 by Bay 61–3606 is independent of Syk in breast cancer cells." (PMID 26720004, 2015). "In previous studies, CuE (1–10 μM) inhibited the pSTAT3 and induced apoptosis in human breast cancer cell lines Bcap37 and MDA-MB-231 and decreased the levels of the anti-apoptotic proteins XIAP, Survivin, and Mcl-1, and increased the level of Bax in human leukemia HL-60 cells." (PMID 25072848, 2014). "The level of MCL-1 protein was significantly down-regulated by transient transfection of miR-26a in both two cell lines (P<0.05), which means the expression of endogenous MCL-1 was regulated by miR-26a in breast cancer cells." (PMID 23750239, 2013). "Thus, combining Bcl-2/Bcl-xL and Mcl-1 inhibition by ABT-737 and GSIXII, respectively, should restore apoptosis sensitivity efficiently and affect survival maintenance, in breast cancer cells." (PMID 22703841, 2012). "In addition, Mcl-1 and survivin expression is dramatically reduced in response to IDR-E804 and apoptosis is induced in breast cancer cells." (PMID 22554053, 2012). "Despite the clear involvement of SRSF5 in MCF-7 and MDA-MB-231 breast cancer cells, this SR protein did not appear to be involved in the alternative splicing of Mcl-1 in JAR cells." (PMID 23284704, 2012). "Pre-treatment with the inhibitor MG132 followed by CHX exposure resulted in no significant change in the Mcl-1 or Bcl-2 levels in the breast cancer cell lines MDA-MB-231, MDA-MB-468 and MCF-7 (data not shown)." (PMID 21730980, 2011). "Inactivation of pERK1/2 with MEK inhibitor U0 126 (data not shown) or nitric oxide donor DETA-NONOate promoted the decline of Mcl-1 levels in breast cancer cell line MDA-MB-468." (PMID 21730980, 2011). "In our study, downregulation of Puma did not decrease Mcl-1 levels or increase CHX-mediated apoptosis in breast cancer cells." (PMID 21730980, 2011).